P2RX7 (purinergic receptor P2X 7)
Diseases named in the same sentence as P2RX7 in open-access papers (continued):
Sharing a sentence is not in itself a finding about the gene and the disease.
tumor (continued). "The use of transplantable murine tumor models has demonstrated that P2RX7 expressed by host immune cells coordinates anti-tumor immune responses 13,14." (PMID 33042257, 2020). "Using the probe which amplifies P2RX7A, B and H (further designed as P2RX7), we observed that P2RX7 was 2.5-fold less expressed in tumor versus non-tumor areas of LUAD." (PMID 33042257, 2020). "In the microenvironment of tumor growth, extracellular high levels of ATP activate P2RX7." (PMID 41007849, 2025). "Rapid tumor growth is in part dependent on P2RX7 stimulation through autocrine/paracrine eATP." (PMID 36803784, 2023). "We previously showed using human tumor lung adenocarcinoma (LUAD) tissues that P2RX7 is expressed in tumor associated immune cells whereas non-immune cells do not express P2RX7." (PMID 36600200, 2023). "Given its ability to induce cell death, one can speculate that the expression of P2RX7 on tumor cells is beneficial." (PMID 37298187, 2023). "Reasonably, breaking this vicious circle by inhibiting P2RX7 might shed light on the development of novel tumor therapy." (PMID 36803784, 2023). "Furthermore, we recapitulate our current knowledge of the production of IL-18 downstream of P2RX7 activation and how IL-18 controls the fate of tumor growth." (PMID 37298187, 2023). "Furthermore, we detected lactate level within tumor tissue and found that c-Myc knockdown almost abrogated P2RX7-stimulated lactate production." (PMID 36803784, 2023). "Thus, we concluded that P2RX7 promoted tumor growth and metastasis and metabolic reprogramming mainly dependent on c-Myc." (PMID 36803784, 2023). "By IHC staining, it was demonstrated that P2RX7 KO could dramatically inhibit Ki67 expression in vivo, an indicator of tumor growth." (PMID 36803784, 2023). "P2RX7 can be considered to be a fine tuner of the tumor microenvironment, given that it is able to induce cell proliferation and death as well as to modulate the immune response through various pathways, notably through the release of IL-18 following the activation of the NLRP3 inflammasome." (PMID 37298187, 2023). "Furthermore, c-Myc mediated metabolic reprogramming was crucial for P2RX7 to promote tumor growth and metastasis." (PMID 36803784, 2023). "P2RX7 has an extensive role in immune cells and tumor onset." (PMID 36741002, 2023). "ENTPD1, IL17A, and P2RX7 were downregulated, while HSP90AA1, PIK3CA, and NT5E were upregulated, indicating that ENTPD1, IL17A, and P2RX7 might negatively affect tumor development and result in better outcome." (PMID 37587188, 2023). "Moreover, early depletion of Tregs in vivo by activation of P2RX7-expressing T cells using the NAD+/ART2 axis (known to activate P2RX7 in mouse T cells) in tumor mouse models increased the anti-tumor effector functions of CD8+ T cells." (PMID 37298187, 2023). "(ii)In addition to participating in purinergic neurotransmission, ATP released from damaged cells can bind to the P2Y2 receptor of macrophages, promoting the infiltration of macrophages in tumor sites, and can also bind to the P2RX7 of DC cells, leading to DC maturation and release of IL-1β." (PMID 36081554, 2022). "This negative feedback mechanism could be particularly relevant in tumor microenvironment, where the activation of the p38 may upregulate P2rx7 gene expression." (PMID 36589747, 2022). "Based on preclinical studies reporting a strong oncogenic role of this receptor, an increase of P2RX7 facilitates cell proliferation even in scenarios of trophic deprivation, promoting tumor cell proliferation, energy production, migration and invasiveness of cancer cells." (PMID 36589747, 2022). "Thus, while overstimulation of the receptor activates a large pore in the membrane that induces tumor cell death and inhibits tumor growth, tonic activation of P2RX7 supports the growth, migration, and invasiveness of tumors in vivo in several types of cancer." (PMID 36589747, 2022).
tumor (continued). "However, P2RX7 overstimulation by high extracellular ATP concentrations is also capable of inducing tumor cell killing." (PMID 34768902, 2021). "New evidence suggests that P2RX7 has an essential role in restraining tumor progression." (PMID 34502169, 2021). "Finally, activation of P2RX7 combined with αPD-1 immune checkpoint inhibitor allows tumor regression, followed by the establishment of a robust immunological memory response." (PMID 33510147, 2021). "Whereas each P2RX7 variant was equally down-regulated in the epithelial compartment of tumor tissues versus adjacent non-tumor tissues, we observed differential up-regulation of P2RX7B in the tumor immune compartment." (PMID 33042257, 2020). "Yet, analysis of sequencing repositories from large tumor panels, including deep sequencing initiatives, does not highlight the preferential selection of mutation or copy number variation in the P2RX7 gene by tumor cells." (PMID 32581786, 2020). "These patients only showed very limited (if any) expression of P2RX7 on tumor cells." (PMID 33042257, 2020). "Indeed, considering that P2RX7 is a pro-apoptotic receptor, it is counterintuitive to imagine that tumor cells express a receptor capable of inducing their own death." (PMID 33042257, 2020). "Exploration of tumor-associated immune cell populations has also led to the discovery that macrophages and microglia are not the only cells to express high levels of P2RX7." (PMID 30003075, 2018). "Notably, targeted inhibition of P2RX7 is crucial as its global blockade reduces the immune and inflammatory responses, which have important anti-tumor effects in some types of malignancies." (PMID 30003075, 2018). "In addition, a treatment exploiting the overexpression of P2RX7 on tumor cells and turning it against the tumor is an appealing proposition." (PMID 30003075, 2018). "Furthermore, how can tumor cells take advantage of P2RX7 for growth and spread and yet survive overexpression of potentially cytotoxic LP in the eATP-rich environment?" (PMID 30003075, 2018). "Thus, the systemic administration of pharmacological P2RX7 blockers should have a potent anti-tumor effect by preventing the high jacking of this receptor by cancer cells." (PMID 30003075, 2018). "However, in some other tumors or cell lines, P2RX7 worked as a tumor suppressor." (PMID 41007849, 2025). "HCLS1 may have a similar function to P2RX7 by affecting tumor cell proliferation and metastasis." (PMID 41007849, 2025). "We further tested whether P2RX7 regulated tumor growth via glucose metabolism in nude mice." (PMID 36803784, 2023). "P2RX7 overexpression facilitated tumor growth, which could be to some extent abolished by 2-DG." (PMID 36803784, 2023). "Therefore, P2RX7 in organs with discontinuous capillaries, or in pathologies affecting capillary permeability (e.g., inflammation or tumor neo-vascularisation) may be under the regulatory control of MMP-2 cleavage balanced by TIMPs." (PMID 30003075, 2018). "Indeed, there are indications that immune suppression following P2RX7 inhibition is a real and potentially significant drawback, as tumors in p2rx7 KO mice show accelerated growth, increased tumor size and metastasis, recruitment and invasion, all of which reflects reduced immune cell activation." (PMID 30003075, 2018). "For example, tumors growing in P2rx7 null mice overexpress CD73, CD39, and A2A in either immune-infiltrating or tumor cells." (PMID 40759630, 2025). "The results of immunochemistry showed that GBP2, HCLS1, P2RX7, and SLC11A1 were more highly expressed in the tumor group than in the normal group." (PMID 41007849, 2025). "The P2RX7 activator, HEI3090, has been shown to augment an anti-tumor immune response, when used in combination with PD-1 immune checkpoint inhibitor." (PMID 39744692, 2025). "We found that P2RX7, MMP15 and MMP16 are upregulated in neurosphere cells, indicating a potential role for these genes in tumor formation." (PMID 41400763, 2025).
tumor (continued). "We obtained the protein expression data of Purinergic genes GNAI2, GNAI3, GNAO1, P2RX4, P2RX7, and PANX1 in normal tissues and tumor tissues in the UALCAN database." (PMID 38180750, 2024). "The results clearly demonstrated that Purinergic genes P2RX7 and PANX1 protein expression levels were significantly higher in tumor tissues than in normal kidney tissues." (PMID 38180750, 2024). "Among the five identified ICDGs, NT5E, HSP90AA1, and EIF2AK3 exhibited heightened expression levels in tumor tissues, while PIK3CA and P2RX7 demonstrated elevated expression levels in normal tissues." (PMID 38575204, 2024). "The five-gene signature’s expression was validated utilizing the TCGA database, with NT5E, HSP90AA1, and EIF2AK3 demonstrating elevated expression levels in tumor tissues, while PIK3CA and P2RX7 exhibited heightened expression in normal tissues." (PMID 38575204, 2024). "The analysis results showed that the expression levels of Purinergic genes GNAI2, GNAI3, P2RX4, P2RX7, and PANX1 were significantly higher in tumor tissues than in normal tissues, consistent with the mRNA expression results." (PMID 38180750, 2024). "We found that the released ATP level was also significantly increased in tumor cells with DU101 or DU102 treatment or Arf1 knockdown, which further stimulated T cell activation through P2RX7." (PMID 39225354, 2024). "CXCL10, P2RX7, TLR3, and TLR4 were significantly upregulated in IS2 tumours in the TCGA cohort, whereas ANXA1, CXCL10, FPR1, IFNAR2, P2RX7, and TLR4 showed significantly higher expression levels in IS4 tumours in the GEO cohort." (PMID 36851274, 2023). "The first showed that the P2RX7 antagonist, AZ10606120, efficiently inhibited the growth of malignant pleural mesothelioma cell lines of patients, when the tumor cell lines were implanted in immunodeficient mice." (PMID 35454832, 2022). "CD91, toll-like receptor 4 (TLR4), and The P2X7 receptor (P2RX7) are expressed by dendritic cells (DCs) and promote phagocytosis of dead cells, presentation of tumor antigens, and production of IL-1β, respectively." (PMID 36081554, 2022). "In this study we characterized the expression levels and the functionality of P2RX7 in LUAD patients and showed that whereas P2RX7 was found to be expressed in both tumor and immune cells, only immune cells expressed a functional receptor." (PMID 33042257, 2020). "The P2RX7B splice variant was differentially upregulated in immune cells (P < 0.001) of the tumor and strong evidence of oligomerization of P2RX7A and B was observed in the HEK expression model, which correlated with a default in the activity of P2RX7." (PMID 33042257, 2020). "Counting among the DAMPs, extracellular ATP can be sensed by DCs through the purinergic receptors P2RX7 and P2RY2, and triggers their migration to the tumor bed and their activation." (PMID 33281620, 2020). "Quite the reverse, tumor cells use this P2RX7 overexpression to their significant advantage though increases in growth, migration, the Warburg effect, VEGF production triggering tumor neo-angiogenesis and MMP release helping its invasion and metastasis." (PMID 30003075, 2018). "Calreticulin, ATP, and HMGB1 bind to CD91, P2RX7, and TLR4, respectively, facilitating dendritic cell (DC) recruitment into the tumor bed (by ATP), the phagocytosis of tumor antigens by DCs (enhanced by CRT), and an optimal antigen presentation to T cells (stimulated by calreticulin and HMGB1)." (PMID 40313247, 2025). "Additionally, high-dose UVA triggered activation of p38 MAPK, upregulation of TNFα, and the regulatory signaling molecule Connective Tissue Growth Factor (CTGF) mRNA expression, while transcription of tumor-suppressors VDR, and P2RX7 were downregulated." (PMID 40328921, 2025). "They bind to scavenger receptors and CD91, P2X purinoceptor 7 (P2RX7), and Toll-like receptor 2/4 (TLR2/4) on immature DCs respectively, facilitating the attraction and maturation of DCs capable of priming or reactivating tumor-specific T cells." (PMID 39987121, 2025).
tumor (continued). "Mechanistically, the activation of P2RX7 leads to an increase in IL-18 production in an NLRP3-dependent manner, which subsequently activates NK cells and CD4+ T cells to produce IFN-γ, thereby enhancing tumor immunogenicity." (PMID 39744692, 2025). "Moreover, to verify the protein expression of the four genes, including ENTPD1, NLRP3, TLR4, P2RX7, the HPA database was applied for inspection of the expression of the proteins deprived from them in LUAD tumor tissues and normal tissues." (PMID 37553698, 2023). "ATP and ANXA1 ligate purinergic receptors of the purinergic receptor P2X 7 (P2RX7) type and formyl peptide receptor 1 (FPR1), respectively, thus facilitating the chemoattraction and homing of migratory cDC1s into the tumor bed, into the proximity of stressed and dying cancer cells." (PMID 37907944, 2023). "Considering that P2RX7 is a pro-apoptotic receptor, it makes sense that tumor cells express a nonfunctional receptor." (PMID 33510147, 2021). "Mechanistically, activation of P2RX7 leads to increased production of IL-18 in a NLRP3-dependent manner, which in turn activates NK and CD4+ T cells to produce IFN-γ and consequently increases tumor immunogenicity." (PMID 33510147, 2021). "In the tumor area, P2RX7 was 15-fold up-regulated in immune cells compared to non-immune cells and the alternative splice variants P2RX7B, H and J were 7-, 6- and 15-fold up-regulated, respectively." (PMID 33042257, 2020). "Herein, we observed that P2RX7 expressed by tumor cells, but also normal epithelial cells, lacked the macropore function, whereas immune cells retained it." (PMID 33042257, 2020). "Further, we analyzed the expression levels of all P2RX7 mRNA in both non-tumor and tumor areas and observed that while P2RX7 was down-regulated in non-immune cells, it was up-regulated in immune cells." (PMID 33042257, 2020). "By comparing normal and tumor tissue we could show that two of the genes—CAMKK2 and P2RX7, were affected at the level of gene expression and protein structure, respectively." (PMID 27171399, 2016). "Moreover, P2RX7 coordinates immunogenic cell death (ICD) and enhances the ability of DCs to activate and present tumor antigens to T cells, positioning it as a positive regulator of the anti-tumor immune response." (PMID 39744692, 2025). "Recent studies indicated that tumor growth in mice lacking P2rx7 does not respond to chemotherapy." (PMID 38195677, 2024). "Accordingly, it has been shown that the expression of P2RX7 on mouse CD8+ T cells enhances mitochondrial functions through calcium influx and AMPK activation, required to support the generation and survival of memory T cells and efficiently eradicate tumor cells." (PMID 37298187, 2023). "Since ATP is normally present inside the cell, eATP constitutes a damage-associated molecular pattern (DAMP), enabling the recruitment and activation of immune cells into the TME, but can also be recognized by P2RX7-expressing non-immune cells, such as tumor cells." (PMID 37298187, 2023). "However, the potential mechanisms by which P2RX7 promotes tumor growth and metastasis are not fully elucidated." (PMID 36803784, 2023). "The purpose of P2RX7’s downregulation is not only to prevent T cell death by protecting antigen-reactive T cells, but also to favor the ionic activity of the receptor and to confer a better fitness of CD8+ T cells, which consequently enhances the control of tumor growth." (PMID 37298187, 2023). "Extracellular ATP release occurs through a variety of mechanisms, including tumor necrosis and apoptosis, vesicular exocytosis, active efflux via ATP-binding cassette subfamily C member 6 (ABCC6) and the ankylosis gene product ANK and diffusion via P2RX7 and Pannexin1 channels." (PMID 35515134, 2022).
tumor (continued). "At this time, we still do not know whether the isoform of P2RX7 expressed by tumor cells corresponds to nfP2RX7, since the only way to characterize its expression relies on the use of an anti-nfP2RX7 antibody, which is not commercially available." (PMID 33042257, 2020). "We explored the hypothesis that the lack of macropore activity in tumor and non-tumor epithelial cells could be the consequence of expression of truncated P2RX7 isoforms, resulting from alternative splicing of P2RX7 mRNA rather than SNPs." (PMID 33042257, 2020). "Another could be the development of positive modulators of P2RX7 LP formation or compounds which effectively upregulate or reinstate P2RX7 LP formation in tumor cells, which overexpress either functional or “non-functional” receptor variants." (PMID 30003075, 2018). "Extracellular ATP can also function through P2RX7 purinergic receptors to initiate NLRP3 inflammasome activation and subsequent IL-1β production that were all shown to be required for the induction of tumor antigen-specific CD8+ T cells following challenge with dying tumor cells." (PMID 23087904, 2012). "Another study found that extracts from an anti-tumorigenic mushroom functioned by activating the same P2RX7/NLRP3 pathway in macrophages, but did not draw a direct link to altered tumor kinetics." (PMID 24795727, 2014). "Compared to adjacent non-tumor tissues, tumor tissues from Gem-R PDAC patients exhibited high expression of P2RX7, suggesting that P2RX7 may serve as an oncogenic factor in Gem-R PDAC." (PMID 41469519, 2025). "The consistent results using two different P2rx7-knocked-out clones rule out possible off-targets of the CRISPR/Cas9 technique used and demonstrate the critical involvement of cancer cell invasiveness in primary tumour growth." (PMID 32825056, 2020).